NLRP3 (NLR family pyrin domain containing 3)
Diseases named in the same sentence as NLRP3 in open-access papers (continued):
Sharing a sentence is not in itself a finding about the gene and the disease.
atherosclerosis (continued). "Most studies reveal a protective role of REV-ERBα in cardiac tissue by inhibiting atherosclerosis risk factors and downregulation of NLRP3 inflammasome." (PMID 35743288, 2022). "Inhibition of NLRP3 was reported to protect against diabetes-associated atherosclerosis via reducing inflammation and improving vascular function." (PMID 35811739, 2022). "Recently, emerging studies report that pyroptosis is associated with both NLRP3 inflammasome and atherosclerosis." (PMID 36304814, 2022). "Several studies have also shown that the NLRP3 inflammasome promotes to the development of atherosclerosis by influencing several pathogenic events, such as oxidative stress, mitochondrial dysfunction, endoplasmic reticulum stress, and lysosomal disruption." (PMID 35844498, 2022). "Other lipids, such as SFAs (palmitate and stearate) and their metabolites ceramides and triglycerides, are also risk factors for atherosclerosis, and they can also trigger NLRP3 inflammasome-dependent pyroptosis in macrophages." (PMID 35844498, 2022). "The NLRP3 inflammasome has been associated with atherosclerosis in many studies by analyzing aortic NLRP3 expression in patients with atherosclerosis." (PMID 36082127, 2022). "The review summarized the current studies associated with autophagy and NLRP3 inflammasome in atherosclerosis." (PMID 36671400, 2022). "NLRP3 is implicated as a driver of inflammation in a range of disorders including neurodegenerative diseases, type 2 diabetes, and atherosclerosis." (PMID 35353387, 2022). "This review summarizes the most recent studies and the underlying mechanisms associated with different autophagic pathways and NLRP3 inflammasomes in vascular inflammation, aiming to provide additional evidence for atherosclerosis research." (PMID 36671400, 2022). "In a diet-induced atherosclerosis mouse model, NLRP3 inflammasome activation was linked to atherosclerosis progression via gene silencing of Nlrp3 in Apoe−/− mice." (PMID 35590369, 2022). "Atherosclerosis is the main cause underlying vascular disease and there are several pieces of evidence pointing out that inflammation and NLRP3 play an important role in this disease." (PMID 35204152, 2022). "NLRP3 has not only been linked to atherosclerosis, but also to other harmful vascular processes, such as abdominal aortic aneurysm (AAA)." (PMID 35204152, 2022). "In the context of CVD, the activation of the NLRP3 inflammasome in macrophages, with the consequent release of IL-1β, has been shown to be implicated in the development of atherosclerosis and the clinical manifestations of the disease." (PMID 36613465, 2022). "NLRP3 can be overexpressed in the aorta of patients with atherosclerosis, making it an important risk factor for the development of and correlation with the severity of coronary artery disease." (PMID 36589841, 2022). "A recent study revealed that even in the absence of the priming step, humanmononuclear cells assemble functional NLRP3 inflammasomes invitro in response to the activation signal, causing inflammation during theearly stage of atherosclerosis." (PMID 39076616, 2022). "Revealed thattransplantation of NLRP3-deficient bone marrow cells into LDLreceptor-deficient mice predisposed to atherosclerosis is associated withinhibition of atherosclerosis." (PMID 39076616, 2022). "The ultimate result of those deleterious processes associated with NLRP3 inflammasome activation is atherosclerosis progression." (PMID 36555579, 2022). "NLRP3-driven inflammatory responses are implicated in atherosclerosis plaque formation, according to emerging evidence." (PMID 36557935, 2022). "Aberrant function of the Nod-Like Receptor Protein 3 (NLRP3) inflammasome, a central mediator in the proinflammatory response, has been associated with atherosclerosis." (PMID 36582742, 2022). "Aberrant activation and dysregulation of the NLRP3 inflammasome have been associated with several inflammatory disorders, including atherosclerosis." (PMID 36582742, 2022).
atherosclerosis (continued). "Lipid deposition,ox-LDL, macrophage transformation into foam cells and other events associatedwith atherosclerosis interact with the NLRP3 inflammasome to promote progressionof the disease." (PMID 39076616, 2022). "The TXNIP/NLRP3 inflammasome signaling is closely associated with the development and progression of atherosclerosis." (PMID 36187801, 2022). "The high concentrations of cholesterol or cholesterol crystals can promote the activation of NLRP3 inflammasome to start inflammation associated with hyperlipidemia or atherosclerosis." (PMID 36425260, 2022). "Here we review the recently described mechanisms about the NLRP3 inflammasome activation, and discuss emphatically the pharmacological interventions using statins and natural medication for atherosclerosis associated with NLRP3 inflammasome." (PMID 35493086, 2022). "Our data suggest that PCSK9 acts as an activator of NLRP3, revealing a new mechanism for NLRP3 involvement in atherosclerosis and underlining the importance of the inflammasome in this pathology." (PMID 36012389, 2022). "Crystalline cholesterol induces lysosomal damage, and it was the first NLRP3 activator associated with atherosclerosis." (PMID 35310965, 2022). "In present study, we firstly demonstrated that Nur77 deficiency significantly promoted NLRP3-mediated inflammatory responses, thus contributing to the development of atherosclerosis." (PMID 35464766, 2022). "It is reported that the activation of the NLRP3 inflammasome is closely associated with the pathogenesis of multiple inflammatory diseases, such as type II diabetes, atherosclerosis, Alzheimer’s Disease, and gout." (PMID 34965184, 2022). "Activation of the NLRP3 inflammasome has previously been demonstrated to play an important role in the severe inflammation underlying atherosclerosis." (PMID 35590369, 2022). "In fact, NLRP3 inflammasome over-activation and the subsequent increase in inflammatory cytokines, especially IL-1β, has been frequently linked to atherosclerosis, diabetes, and related chronic sequels." (PMID 35204152, 2022). "A microbiota metabolite, Trimethylamine-N-oxide (TMAO), recently has been linked with endothelial inflammation and atherosclerosis, due to its ability to initiate lysosomal dysfunction and NLRP3 inflammasome activation." (PMID 34631209, 2021). "A study of nicotine exacerbating atherosclerosis showed that increased intracellular ROS caused macrophages pyroptosis, which is manifested by the assembly of NLRP3 inflammasome, the cleavage of caspase-1 and the increase of IL-1β, IL-18, and GSDMD production." (PMID 34122076, 2021). "NLRP3-mediated induction of atherosclerosis has been associated with a host of causal factors including hypoxia, cholesterol crystals and oxLDL, and disturbed flow." (PMID 35002720, 2021). "As described in the previous chapters, cholesterol-driven NLRP3 inflammasome activation is a causative factor on atherosclerosis and occlusive aortic disease." (PMID 34572082, 2021). "Recent studies have shown that there is a correlation between atherosclerosis-associated inflammation and the accumulation of free cholesterol in macrophages, which leads to NLRP3 inflammasome activation." (PMID 34860135, 2021). "Autophagy has been implicated in the pathogenesis of atherosclerosis and has been shown to inhibit the NLRP3 inflammasome activation and apoptosis and to relieve oxidative stress." (PMID 34377468, 2021). "Our study unraveled for the first time that lipid raft–mediated α1-nAChR accumulation was the underlying mechanism for nicotine-induced NLRP3 inflammasome activation in macrophage and for nicotine-accelerated atherosclerosis." (PMID 34490270, 2021). "Each of these cytokines, as well as activation of the NLRP3 inflammasome itself, has been implicated in endothelial dysfunction and atherosclerosis pathogenesis." (PMID 34326395, 2021).
atherosclerosis (continued). "Inflammasomes composed of NOD-like receptor containing pyrin domain 3 (NLRP3) are highly associated risk factors for deteriorated atherosclerosis." (PMID 33626512, 2021). "The NLRP3 inflammasome is associated with several human disorders, including Alzheimer's disease, atherosclerosis, and allergy airway inflammation." (PMID 33613822, 2021). "The inflammatory response mediated by the NOD-like receptor family pyrin domain-containing 3 (NLRP3) inflammasome is associated with atherosclerosis progression." (PMID 35004893, 2021). "The authors concluded that activation of the NLRP3-inflammasome provides a general pattern in the inflammatory process of the underlying atherosclerosis, whereas the NLRP1-inflammasome seems to be specific for the pathogenesis of AOD." (PMID 34572082, 2021). "Statin therapy can down-regulate NLRP3, cathepsin-B, and downstream mediators such as IL-1β, which play a significant role in inflammation associated with atherosclerosis and reduce NLRP3 gene expression in PBMCs of CVD patients." (PMID 32378144, 2021). "Increased aortic levels of sterol regulatory element binding protein (SREBP)-1 were associated with elevated expression of NLRP3 inflammasome components in a porcine model of atherosclerosis and DM." (PMID 32751658, 2020). "Deregulation of the NLRP3 signaling cascade is associated with numerous inflammatory and metabolic diseases including rheumatoid arthritis, gout, atherosclerosis or type 2 diabetes." (PMID 32849554, 2020). "Dysregulated inflammasome activity, in particular NLRP3 inflammasome, was linked to several inflammatory diseases, such as diabetes, atherosclerosis, inflammatory bowel disease, multiple sclerosis, vitiligo, and gouty arthritis." (PMID 33339319, 2020). "Since strong evidence shows that NLRP3 is a potential marker in other diseases such as RA, atherosclerosis, gout and colorectal cancer, we detailed the evidence that indicates the association of NLRP3 with OA in the following sections." (PMID 33014529, 2020). "The NLRP3 inflammasome has been implicated in the pathogenesis of metabolic disorders such as type 2 diabetes, atherosclerosis, obesity, and gout." (PMID 33603747, 2020). "The NLRP3 inflammasome has been implicated in the pathogenesis and progression of atherosclerosis, especially in potentiating sterile inflammation." (PMID 32751530, 2020). "Our results presented here show, for the first time, that Tan IIA is a potent inhibitor of the NLRP3 inflammasome—a key pathogenic driver of atherosclerosis." (PMID 33290264, 2020). "Many investigations have revealed the association between NLRP3 inflammasome and CVDs, including atherosclerosis, ischemia/reperfusion (I/R) injury and heart failure induced by pressure overload or cardiomyopathy." (PMID 32508013, 2020). "HIV-1 infection can mediate NLRP3 inflammasome activation, thus potentiating a pro-inflammatory state and increasing risk of atherosclerosis." (PMID 32596261, 2020). "Since activation of the NLRP3 inflammasome is essential for the host immune response, NLRP3 is associated with many diseases, including Alzheimer’s disease, atherosclerosis, gout, and inflammatory bowel disease." (PMID 33182702, 2020). "NLRP3 has also been implicated in the pathogenesis of a number of complex diseases, notably including metabolic disorders such as type 2 diabetes, atherosclerosis, obesity, and gout." (PMID 32148650, 2020).
atherosclerosis (continued). "For example, transplantation of bone marrow cells from NLRP3- or IL1-deficient mice into mice models of atherosclerosis resulted in significant amelioration of aortic atherogenesis." (PMID 32358544, 2020). "Abnormal autophagy or mitophagy (the selective autophagic degradation of mitochondria) has been implicated in the aberrant activation of the NLRP3 inflammasome in metabolic diseases such as atherosclerosis and type 2 diabetes." (PMID 32751530, 2020). "Animals studies of humanized mice that connect the risk of HIV-1 infection, NLRP3 activation, and the development of atherosclerosis are necessary." (PMID 32596261, 2020). "It has been reported that the NLRP3 inflammasome plays an important role in inflammation-associated atherosclerosis and obesity, and a study showed that NLRP3 inflammasome levels are increased in HT, but the specific mechanism in HT is not clear." (PMID 31824415, 2019). "It has been reported that cherry consumption can reduce atherosclerosis risk factors, and that the NLRP3 inflammasome pathway is centrally involved in the recognition of triggers that appear during physiological aging and metabolic stress." (PMID 31569594, 2019). "The proposed mechanism for the link between clonal hematopoiesis and atherosclerosis involves increased NLRP3 inflammasome-mediated IL1β secretion in TET2-deficient macrophages in mice." (PMID 31712595, 2019). "Experimental observations in a murine model have demonstrated that enhanced atherosclerosis withTET2 mutations is likely due to increased activity of NLRP3 inflammasome in monocytes." (PMID 31448091, 2019). "NLRP3 has been associated with the development of cancer, atherosclerosis, currently viewed as predictor for chronic myeloid leukemia and novel diagnostic biomarker for early detection for diabetic nephropathy." (PMID 31551961, 2019). "In our study we observed a significant NLRP3 inflammasome inhibition by whichever type of CE-loaded NPs, and stressed the importance of cherry in atherosclerosis risk factors prevention." (PMID 31569594, 2019). "Lyosomal destabilization is also associated with NLRP3 activation and can be induced by a number of molecules, including cholesterol crystals in macrophages linking atherosclerosis progression with inflammation." (PMID 29686666, 2018). "Inappropriate activation of NLRP3 drives a chronic inflammatory response and is implicated in several non‐communicable diseases, including gout, atherosclerosis, type II diabetes and Alzheimer's disease." (PMID 29331080, 2018). "Cholesterol crystals in vascular plaques of atherosclerosis are important activators of the NLRP3 inflammasome and have been shown to prevent atherosclerosis in NLRP3-deficient mice." (PMID 30514828, 2018). "Blockage of NLRP3 signaling inhibits the progression of atherosclerosis in apolipoprotein E-deficient (ApoE−/−) mice treated with a high-fat diet." (PMID 30405440, 2018). "Future studies should focus on other potential targets implicated in atherosclerosis pathogenesis; i.e., the NLRP3 inflammasome or specific or multiple chemokines." (PMID 29954107, 2018). "Further studies investigating the mechanisms of NLRP3 gene polymorphisms on atherosclerosis are necessary." (PMID 29850543, 2018). "NLRP3 inflammasome has been implicated in the pathogenesis of a wide variety of diseases, including Alzheimer’s disease, atherosclerosis, and type 2 diabetes." (PMID 30315268, 2018). "In terms of CVD prevention, canakinumab was particularly attractive since known atherosclerosis risk factors upregulate IL-1β via the NLRP3 inflammasome." (PMID 29922680, 2018). "It was also reported that NLRP3 inflammasome mRNA level was upregulated in a pig aorta in a diabetes mellitus-associated atherosclerosis." (PMID 30254716, 2018). "A recent study has shown genetic variants of NLRP3 in the pathogenesis of atherosclerosis, and NLRP3 and inflammatory cytokines have also been proposed as new cardiovascular risk biomarkers." (PMID 29245937, 2017).
atherosclerosis (continued). "Further study clarifying the molecular mechanisms of NLRP3 inflammasome activation would serve to develop a novel therapeutic approach to atherosclerosis and other inflammatory diseases, which are caused by crystals and particulate matter." (PMID 29259717, 2017). "The macrophage NLRP3 inflammasome has been implicated in the pathogenesis of metabolic diseases, including type 2 diabetes and atherosclerosis." (PMID 28729463, 2017). "Excessive activation of NLRP3 inflammasome has also been linked to a variety of inflammatory disorders or metabolic disorders, such as Alzheimer’s disease, atherosclerosis, gout, and obesity." (PMID 29375379, 2017). "Since several studies have shown that IL-1β contributes to the progression of atherosclerosis, it is expected that the deficiency of NLRP3 inflammasomes prevents atherosclerosis." (PMID 29259717, 2017). "Cholesterol crystal (CHC), a hallmark of atherosclerosis, initiate inflammation via nod-like receptors nucleotide-binding domain and leucine-rich repeat pyrin-3 domain (NLRP3) inflammasome leading to IL-1β and TNF production." (PMID 29133791, 2017). "Further studies with larger sample sizes, longer follow-up periods, and more detailed examination of the mechanism of G allele in atherosclerosis should be conducted to assess the effect of NLRP3 rs10754558 gene polymorphism on CAD." (PMID 27110561, 2016). "The polymorphism of NLRP3 influences the inflammasome activation in atherosclerosis and in turn the susceptibility of people to CAD." (PMID 27110561, 2016). "A number of recent landmark studies have implicated the activation of the NLRP3 inflammasome, in the progress of atherosclerosis." (PMID 24999295, 2014). "Crystalline cholesterol was proposed to cause atherosclerosis by acting as a danger signal and initiating inflammation through the NLRP3 inflammasome." (PMID 24137163, 2013). "Increased NLRP3 inflammasome components are implicated in the pathology of obese individuals with type 2 diabetes and atherosclerosis." (PMID 23825667, 2013). "For instance, the NLRP3 inflammasome has been linked to obesity, insulin resistance, atherosclerosis, and Alzheimer’s disease." (PMID 24137163, 2013). "In conclusion, the present study uncovers a previously unrecognized role of SREBP in atherosclerosis and its functional association with NLRP3 inflammasome-driven inflammation." (PMID 23825667, 2013). "Chronic inflammation and activation of NLRP3 inflammasome have been implicated in atherosclerosis and fatty liver disease." (PMID 23825667, 2013). "For example, LDL-receptor-deficient mice (genetically prone to atherosclerosis) that are reconstituted with bone marrow cells from mice that lack NLRP3, ASC, or IL-1β are remarkably resistant to plaque formation." (PMID 23087690, 2012). "Lysosomal destabilization is also associated with the NLRP3 activation induced by cholesterol crystals in macrophages, probably involved in the inflammation promoting atherosclerosis." (PMID 22411934, 2012). "Similarly, in cardiovascular diseases, targeting PCSK9 lowers cholesterol levels, while NLRP3 knockout reduces myocardial inflammation, improving atherosclerosis and decreasing cardiovascular event risk." (PMID 40255230, 2025). "Furthermore, the stability of Nrf2 and suppression of NLRP3 are associated with the atheroprotective action of dong quai meconin in ApoE-/- mice, highlighting its potential as a therapeutic agent for atherosclerosis." (PMID 40099271, 2025). "OGG1 deficiency has been shown to cause a significant increase in oxidized mitochondrial DNA (mtDNA), which, in turn, has been linked to the activation of the NLRP3 inflammasome, the secretion of interleukin-1 beta (IL-1β), and the acceleration of atherosclerosis." (PMID 40867876, 2025).